ING4 (inhibitor of growth family member 4)
Diseases named in the same sentence as ING4 in open-access papers (continued):
Sharing a sentence is not in itself a finding about the gene and the disease.
tumor (47 papers, 2007 to 2025). "Patients with GZMB-low/ING4-low tumors had the worst survival outcomes (HR = 2.80, 95% CI 1.36–5.75, p = 0.0004), supportive of the idea that the GZMB-low immune environment contributes to ING4-deficient tumor progression." (PMID 38968186, 2024). "Dysregulated NF-kB due to ING4 deficiencies resulted in aggressive tumor behaviors such as increased cell survival, migration, and angiogenesis." (PMID 38968186, 2024). "Accordingly, ING4 deficiencies have been implicated in many cancer types and several non-neoplastic diseases." (PMID 38968186, 2024). "Deficiencies in the ING4 tumor suppressor are associated with advanced stage tumors and poor patient survival in cancer." (PMID 38968186, 2024). "ING4 downregulation, loss of expression and mutations have been observed in many tumors and cancer cell lines, supporting its potential as a tumor suppressor that regulates several biological and pathological processes." (PMID 36077605, 2022). "Consistently, ING4 associates with the NF-κB complex and leads to the downregulation of NF-κB target genes, indicating that ING4 is a tumor suppressor." (PMID 36077605, 2022). "Missense mutations in the PHD motif of ING1 and ING4 abolished their tumour suppressive nuclear function." (PMID 34685579, 2021). "N214D mutations dramatically lowered the ability of ING4 to act as a tumor suppressor, i.e., inhibition of tumor cell proliferation, cell growth and migration, and sensitization to cell death." (PMID 31390718, 2019). "Mice deficient for ING4 are hypersensitive to lipopolysaccharide (LPS) treatment and display elevated cytokine responses, but fail to form spontaneous tumours." (PMID 31905726, 2019). "For a better understanding of the role of ING4 in pathogenesis, we focussed on the mechanisms underlying ING4-related tumor suppression." (PMID 30643005, 2019). "Conversely, deletion or down-regulation of ING4 is firmly associated with high tumor grade, metastasis, and poor prognosis in a number of cancers, including breast carcinoma, glioblastoma and gastric carcinoma." (PMID 29137298, 2017). "ING4, a potential tumor suppressor, is implicated in cell cycle arrest, apoptosis, cell migration and angiogenesis." (PMID 27806345, 2016). "Immune marker analyses of Ing4-deleted tumors revealed a significant increase in tumor-associated macrophages (Gr-1loCD11b+F4/80+) and a decrease in granzyme B-positive (GzmB+) CD4+ T cells, indicating a suppressive and/or less tumoricidal immune microenvironment." (PMID 38968186, 2024). "Furthermore, ING4 expression in normal fibroblasts induces the senescence-associated secretory phenotype, promoting tumor progression in mice." (PMID 36077605, 2022). "It was also suggested that the ING4 mutant may be a dominant negative allele that interferes with the tumor-suppression function of the wild-type allele and contributes to tumorigenesis." (PMID 30643005, 2019). "In another study, a cell-penetrating peptide conjugated to DGL for delivery of pcDNA3.1-ING4, a plasmid encoding tumor suppressor gene inhibitor of growth 4 (ING4), demonstrated enhanced apoptosis of U87 tumor cells and resulted in increased survival of mice in comparison to treatment with DGL/pDNA." (PMID 30654536, 2019). "We identified ING4 in a genetic screen for candidate tumor suppressors that could suppress loss of contact inhibition in tissue culture." (PMID 23056468, 2012). "Inhibitor of growth family member 4 (ING4) languished in relative obscurity until the past three years when it emerged to function as a tumor suppressor gene, repressing cell proliferation, tumor growth, loss of contact inhibition and angiogenesis." (PMID 19250543, 2009). "Since NF-kB is a key transcription factor that mediates inflammatory response including cytokine production, we hypothesized that ING4-deficient tumors may harbor an immune microenvironment resulting from aberrant NF-kB activity, which in turn contributes to aggressive tumor progression." (PMID 38968186, 2024).
tumor (continued). "In addition, as inflammation has emerged as a hallmark of cancer in general, the ING4/NF-κB gene signature may represent one of the inflammatory gene signatures associated with tumor progression and aggressive disease in other cancer types." (PMID 23056468, 2012). "The results showed that a high percentage of ING4-low/pp65-high tumor patients were lymph node-positive, compared to the other ING4/pp65 expression combination tumor groups (50% vs 26–38%)." (PMID 38968186, 2024). "ING3’s diminished nuclear expression in breast cancer correlates with aggressive disease via p21 signaling, while ING4’s involvement in multiple regulatory pathways, including the NF-κB/miR-155 axis, mitigates tumor progression." (PMID 38813086, 2024). "For further analysis of the effect of S150A mutant on NSCLC immune escape, implanted tumor model was performed using ING4 or S150A mutant stably expressed LLC cells." (PMID 37870169, 2023). "Collectively, in NSCLC, CK2 induced ING4 ubiquitination and degradation, which in turn increased PD‐L1 protein level and inhibited T cell activity, consequently, promoted tumor immune escape." (PMID 37870169, 2023). "The results showed that ING4‐S150A mutant significantly decreased tumor growth and tumor weight, which was in accordance with significantly reduced PD‐L1 protein level in tumors." (PMID 37870169, 2023). "Consistently, ING4 knockout markedly decreased cytotoxic T cell activity and CD8+ T cell numbers, suggesting that loss of ING4 facilitated tumor immune escape by inhibiting T cell activity and proliferation, which was involved in increased PD‐L1 protein level." (PMID 37870169, 2023). "ING4 acts as an autophagy receptor to induce PD‐L1 autophagic degradation leading to inhibition of tumor immune escape, whereas CK2 can induce ING4‐S150 phosphorylation and degradation by JFK ubiquitin ligase resulting in tumor immune escape." (PMID 37870169, 2023). "A recent study reported that ING4 exerts a marked inhibitory effect on tumour cell spread, migration and invasion." (PMID 35075768, 2022). "As a valued member of the ING family, ING4 has been revealed to function as a formidable tumour suppressor due to its significant role in the modification of chromatin modification, cell growth, cell invasion and vascularization." (PMID 35331235, 2022). "The tumor-bearing experiment showed that tumors arising from ING4 stably overexpressed 786-O cells tended to be much larger and grew faster than those developed from the control cells." (PMID 35496267, 2022). "The inhibitor of growth family member 4 (ING4) is one of the ING family genes, serves as a repressor of angiogenesis or tumour growth and suppresses loss of contact inhibition." (PMID 35075768, 2022). "Inhibitor of growth family member 4 is a candidate tumour suppressor gene that exerts the tumour‐suppressive effect via multiple pathways in various tumours." (PMID 35075768, 2022). "Inhibitor of growth 4 (ING4) is a well-known tumour suppressor, and some reports have shown that the ING4 expression level is remarkably downregulated in tumour tissues by miR-650." (PMID 35331235, 2022). "Growth inhibitory factor inhibitor of growth 4 (ING4), as an intracellular tumor growth inhibitory factor, can significantly inhibit the growth of tumor cells inducing cell cycle changes and cell apoptosis." (PMID 34685354, 2021). "In detail, ING4_v4 completely reversed the tumour suppressive inhibition of filopodia/lamellipodia formation mediated by ING4 full-length." (PMID 34685579, 2021). "The coexpression of the ING4 and IL-24 double genes can selectively inhibit tumor angiogenesis and the growth of tumor cells through pathways both inside and outside of the cells." (PMID 34685354, 2021).
tumor (continued). "Analogous to ING3 in PC, ING4 splicing isoforms, missing the full nuclear localization sequence (NLS) (ING4_v2 and ING4_v4), lose tumour suppressive effects, which is rather a characteristic for full-length ING4 (ING4_v1)." (PMID 34685579, 2021). "Although the uptake of the complexes by cells has been identified, the expression of the ING4-IL-24 double gene after transfection of the complexes and the inhibitory effect on tumor cells still needs to be further explored." (PMID 34685354, 2021). "In agreement with previous work showing that SASP stimulates tumour progression in the tissue microenvironment, these ING4-induced senescent cells promote tumour growth in mice." (PMID 33925563, 2021). "In vivo and in vitro studies have reported that ING4 functions in pathways important for cancer hallmarks, such as cell-cycle arrest, apoptosis, autophagy, contact inhibition, hypoxic adaptation, tumor angiogenesis, invasion, and metastasis." (PMID 31752342, 2019). "A novel variant of the replication-competent oncolytic herpes simplex virus HSV1716 that expresses Ing4 (HSV1716Ing4) more efficaciously enhances the oncolytic potency of HSV1716 alone during infection of human tumor cells, both in vitro and in vivo." (PMID 30643005, 2019). "In the same study, the effect of ING4 on the cell cycle was analyzed via FACS analysis in the A549 tumor cells: A significant reduction in S phase, as well as an increase in the G2/M phase, was the result of Ad-ING4 treatment as compared to PBS treatment." (PMID 31390718, 2019). "In the Ad-ING4 treated mice, tumor growth was significantly attenuated as compared to the controls (p < 0.0001)." (PMID 31390718, 2019). "Here, we outline some evidence that abnormalities in ING4 expression and function contribute to the etiology of other non-neoplastic diseases." (PMID 30643005, 2019). "Recent scientific developments have greatly expanded our knowledge of ING4 in some non-neoplastic diseases in multiple organ systems, including respiratory, cardiovascular, urinary, immune, nervous system, and skin." (PMID 30643005, 2019). "We also present the current understanding concerning the role of ING4 in the development of neoplastic and non-neoplastic diseases." (PMID 30643005, 2019). "ING4 suppresses tumor invasion and metastasis via reversal of EMT through down-regulation of Snail1 and through a switch from N-cadherin to E-cadherin, principally by targetting the Wnt/β catenin signaling pathway." (PMID 30643005, 2019). "In tissues of gastrointestinal stromal tumors, the low expression level of ING4 has been found to correlate with tumor risks, in addition to metastasis and invasion." (PMID 30643005, 2019). "Consistent with this, deletion of ING4 promoted tumor vascularization in SCID mice and reduced expression of several NF-κB target genes involved in angiogenesis." (PMID 31752342, 2019). "IHC analysis using anti-ING4 antibody confirmed expression of ING4 in the tumor tissues following by combined treatment." (PMID 29137298, 2017). "Since our CRC cohort showed that ING4 expression was associated with metastasis, and angiogenesis is widely believed to be an important step for tumor metastasis, here we further study the function of ING4 expression in CRC angiogenesis." (PMID 27806345, 2016). "We also thought to assess the utility of CRAd arming with ING4 gene, which was previously shown to provide growth suppression of several tumor types, when being expressed alone or together with IL-24 gene using replication-incompetent Ad vectors." (PMID 27349517, 2016).
tumor (continued). "CD9 (12p13.31) regulates multiple cellular functions such as cell adhesion, migration, apoptosis, and tumor cell motility, ING4 (12p13.31) is involved in cell cycle arrest, apoptosis and senescence, and BCL-G (12p13.2) plays a role in apoptosis." (PMID 26293672, 2015). "The tumor inhibition rate of the mice in the Ad-ING4 group (33.17%±5.24%) was statistically different from that of the mice in the Ad-GFP group (1.31%±0.31%; P < 0.05)." (PMID 24581166, 2014). "It was earlier shown that in the presence of the human tumour suppressor proteins ING4 and ING5, Jade-1 targets the chromatin through interaction with H3K4me3 modifications." (PMID 24267901, 2013). "We then correlated ING4 IHC scores with pathologic features including histologic subtype, tumor size, BRE grade, and lymph node status." (PMID 23056468, 2012). "ING4, a tumor suppressor, mediates chromatin modification and has a suppressive effect on tumorigenesis and innate immunity." (PMID 23028750, 2012). "In the same tumor set, we found that low ING4 expression correlated with high levels of nuclear phosphorylated p65/RelA (p-p65), an activated form of NF-κB (p = 0.018)." (PMID 23056468, 2012). "We compared the ING4 transcript levels between the disease-free and recurrent tumor cohorts using a dot plot and found that primary tumors from patients who later recurred contained significantly reduced ING4 transcript levels (p = 0.0181)." (PMID 23056468, 2012). "We compared the expression of 25 genes between ING4-low and ING4-high tumors by assigning an “ING4/NF-κB gene score” to each tumor." (PMID 23056468, 2012). "The known members of inhibitor of growth (ING) gene family are considered as candidate tumor suppressor genes, ING4, a novel member of ING family, is reported to negatively regulate the cell growth with significant G2/M arrest of cell cycle in HepG2 cells." (PMID 19508737, 2009). "Inhibitor of growth family member 4 (ING4) has recently attracted much attention as a tumor suppressor gene, due to its ability to inhibit cancer cell proliferation, migration and angiogenesis." (PMID 19250543, 2009). "Similarly, ING4 suppresses tumorigenesis by promoting pathologic cell cycle arrest, apoptosis, autophagy, contact inhibition, and hypoxic adaptation, while impeding tumor angiogenesis, invasion, and metastasis." (PMID 38813086, 2024). "How tumor expression of ING4 regulates the CD4 CTL fate in the TME is unclear." (PMID 38968186, 2024). "The mechanism underlying ING4‐ and OSM‐mediated negative regulation of tumour growth remains largely unknown." (PMID 35075768, 2022). "However, it has been revealed to be frequently decreased in various human tumours, and the variation in ING4 markedly contributes to cancer development." (PMID 35331235, 2022). "Interestingly, the Ing4−/− mouse model is viable; the mice developed normally and remained free of tumours over the 20-month period investigated." (PMID 33925563, 2021). "Moreover, inhibitor of growth protein 4 (ING4) was identified as a tumour suppressor that directly interacts with RARβ." (PMID 33805295, 2021). "Several underlying mechanisms remain unclear and need further confirmation; nevertheless, these studies provide a basis for exploring ING4 as a potential therapeutic target in non-neoplastic diseases." (PMID 30643005, 2019). "Interestingly, the function of ING4 shares similarities with that in tumor development, including regulation of growth, proliferation, migration, and cell death." (PMID 30643005, 2019). "In this way, ING4 affects tumor angiogenesis and directly influences brain tumor growth." (PMID 30643005, 2019).
tumor (continued). "As ING4 has additional functions that may directly regulate tumor suppression, the extent to which this mechanism influences tumor behavior should be investigated further." (PMID 30643005, 2019). "Tumor-suppressive properties of ING4 are thus reversed by the cancer-promoting miR-761." (PMID 31390718, 2019). "Moreover, in tumor-bearing athymic mice, intratumoral injections of adenovirus-mediated ING4 (Ad-ING4) suppressed tumor growth and reduced tumor microvessel formation." (PMID 30643005, 2019). "ING4 may also induce apoptosis through negative regulation of NF-κB signaling and via cooperating with other tumor suppressors." (PMID 29137298, 2017). "Here, we investigated whether ING4 could inhibit Sp1 transcriptional activity to exert its suppressive effect on tumor angiogenesis." (PMID 27806345, 2016). "The inhibitor of growth 4 (ING4) is an important tumor suppressive gene." (PMID 24581166, 2014). "Both tumor weight and volume in the Ad-ING4 group were significantly decreased." (PMID 24581166, 2014). "Previous researches have shown that ING4 could function as tumor suppressor in human cancers by regulating the Bcl-2 family proteins." (PMID 23991130, 2013). "Tumors with low ING4 protein staining frequently have advanced tumor features." (PMID 23056468, 2012). "Inhibitor of Growth 4 (ING4) is a member of the ING tumor suppressor family and has been shown to play a role in many cancer-related cellular processes including cell proliferation, apoptosis, migration, angiogenesis, contact inhibition, DNA damage response, and hypoxia." (PMID 23056468, 2012). "Since NF-kB is a mediator of immune response, the ING4/NF-kB axis is likely to elicit tumor-immune modulation resulting in a TIME that may contribute to disease progression, but the immune composition in ING4-deficient tumors has not been characterized to date." (PMID 38968186, 2024). "Moreover, ING4/S150A mutant significantly inhibited tumor immune escape compared to wild type ING4." (PMID 37870169, 2023). "Here, we explored whether ING4 could promote tumor growth and metastasis in vivo." (PMID 35496267, 2022). "Effects were additive for ING4 and IL-24, and in addition up-regulation of the tumor suppressors p21, p27, fas cell surface death receptor (Fas), Bax, and the apoptosis-promoting cleaved caspases-8, -9, -3, and down-regulation of the tumor-promoter Bcl-2 apoptosis regulator (Bcl-2) was observed." (PMID 31390718, 2019). "The authors mention that this finding, indicating inhibition of tumor cell growth via reducing the S phase and an increase in the G2/M phase, differs from previous reports, where G2/M phase arrest was described as a result of adenovirus-mediated ING4 expression in a HepG2 liver cancer cell line." (PMID 31390718, 2019). "Numerous published in vivo and in vitro studies have shown that ING4 is responsible for important cancer hallmarks such as pathologic cell cycle arrest, apoptosis, autophagy, contact inhibition, and hypoxic adaptation, and also affects tumor angiogenesis, invasion, and metastasis." (PMID 30643005, 2019). "In pancreatic and non-small-cell lung cancer, enhanced antitumor effects elicited by Ad-ING4, in combination with radiotherapy, have been reported to be synergistically closely connected to the activation of apoptotic pathways and inhibition of tumor angiogenesis." (PMID 30643005, 2019). "Therefore, expression of SV40-miR-S1-5p may inhibit ING-4 expression, leading to tumor cell growth, invasion, angiogenesis, and activation of the AKT and ERK1/2 signaling pathways, similarly to miR-423-5p." (PMID 30126238, 2018). "Thus, it appears that down-regulation of ING4 may promote tumor progression in cancers originating from different tissue types." (PMID 23056468, 2012). "The inhibitor of growth family member 4 (ING4) is one of the ING family genes, a novel tumour suppressor gene family." (PMID 35075768, 2022).